CDKN2A (cyclin dependent kinase inhibitor 2A)
Diseases named in the same sentence as CDKN2A in open-access papers (continued):
Sharing a sentence is not in itself a finding about the gene and the disease.
melanoma (continued). "Previously, it has been shown that the penetrance of CDKN2A mutations is greater in a high-risk cohort, compared to cases identified through screening of an unselected sample of melanoma cases." (PMID 25803691, 2015). "Recently, in malignant melanoma a CDKN2A deficient mouse cell line demonstrated MET gene amplification." (PMID 25633809, 2015). "Patients with CDKN2A mutations have a high risk of developing melanoma, as well as other tumors, the most common of which is pancreatic cancer." (PMID 25874698, 2015). "The most common high-penetrance melanoma predisposition gene is cyclin-dependent kinase inhibitor 2A, which encodes two independent predisposition genes, CDKN2A/p16 and CDKN2A/ARF." (PMID 26694476, 2015). "It has previously been shown that MC1R variants increased the risk of melanoma in CDKN2A mutation carriers, however in Italian CDKN2A mutations carriers, who have few MC1R variants, other factors influence the risk of developing CM." (PMID 25803691, 2015). "Penetrance of CDKN2A mutations regarding melanoma risk is thus proven to be subject to low-risk genetic variants in other genes." (PMID 26111702, 2015). "The age-specific penetrance for CM in CDKN2A mutation carriers is high in Denmark, as in other high incidence melanoma countries, and MC1R variants modulate the penetrance of CM and the risk of MPM." (PMID 25803691, 2015). "Overall, we analysed CDKN2A in 304 unrelated melanoma cases suspected of a hereditary predisposition to CM and found a pathogenetic mutation in 3.9%." (PMID 25803691, 2015). "In fact, it has been known that there are common genetics between melanoma and plasmacytoma such as CDKN2A germline mutation in prenext generation sequencing (NGS) era." (PMID 26098547, 2015). "Currently, research on genetic modifiers in CDKN2A mutation carriers is mainly focused on identifying low-risk variants that influence melanoma risk." (PMID 26111702, 2015). "In 107 individuals with MPM or melanoma before 40 years, we found 3 CDKN2A mutations, all in individuals with MPM, first diagnosed with CM aged 28, 33, and 40 years, respectively." (PMID 25803691, 2015). "Only the gene body of MGMT showed a low level of methylation increase in CDKN2A-mutated patients compared to sporadic melanoma patients (2% increase in the methylation level, P = 0.02)." (PMID 26106605, 2015). "We found that population-based melanoma cases recruited at different latitudes had very similar probabilities of carrying a pathogenic mutation of the CDKN2A gene of 2.0-2.5%." (PMID 25780468, 2014). "The CDKN2A locus encodes for both proteins p16INK4a and p14ARF and accounts for susceptibility in 25–40% of melanoma families." (PMID 24743186, 2014). "This gene is known as a melanoma susceptibility gene and mutations carrier in CDKN2A, correlated with a higher risk of BC." (PMID 25077705, 2014). "We report a large study aimed at characterizing the prevalence and predictors of pathogenic CDKN2A mutations for melanoma cases." (PMID 25780468, 2014). "To date, CDKN2A is the major gene associated with the high risk inherited in melanoma prone families and in multiple primary melanoma patients." (PMID 24742402, 2014). "Although it has been demonstrated in experimental models that a mutation in NRAS is capable of inducing melanoma in Cdkn2a-deficient mice, NRAS mutations occur in the congenital nevi at a similar frequency to melanoma." (PMID 24959217, 2014). "While the genetic basis for NST remains largely unidentified, several genes associated to melanoma predisposition besides CDKN2A have been recently identified." (PMID 24884915, 2014).
melanoma (continued). "To date, CDKN2A is the major gene responsible for increased melanoma susceptibility in high-risk pedigrees." (PMID 24742402, 2014). "Previous studies suggest that genetic variation of some cytokines or their receptors influence melanoma susceptibility and even modify the risk in melanoma-prone families with CDKN2A mutations." (PMID 24742402, 2014). "The best-established high-risk loci for melanoma susceptibility are the genes CDKN2A, located on chromosome 9p21, and CDK4 on 12q14." (PMID 24743186, 2014). "Several studies have reported that patients with melanoma and a CDKN2A mutation have an earlier age of onset and an increased risk of multiple primary melanomas (MPM)." (PMID 25893138, 2014). "Carriers of a CDKN2A mutation had a significantly earlier age of melanoma onset (mean: 37.51 vs 54.19 year), p<0.05." (PMID 25893138, 2014). "Missense mutations in CDKN2A genes were also described in one French and two Italian families reporting melanoma associated with meningioma and neuroblastoma respectively." (PMID 24884915, 2014). "Although CDKN2A mutation frequency in sporadic melanomas is low, CDKN2A mutation analysis to our opinion is worth trying, as there is a substantial difference in the prognosis between a second primary melanoma and a melanoma metastasis." (PMID 25593912, 2014). "Although heterozygous loss of CDKN2A is sufficient to confer a 67% lifetime risk of melanoma, the mechanisms responsible for tumor enhancement still have to be clarified." (PMID 24742402, 2014). "Germline mutations in high-penetrance melanoma predisposing genes CDKN2A and CDK4 have been found in 20% of familial melanoma cases." (PMID 24982914, 2014). "A high melanocytic nevi count is the strongest known risk factor for melanoma and a potent predictor of mutant CDKN2A gene carrier status." (PMID 24742402, 2014). "The pigmentation related gene MC1R acts as a moderate melanoma risk gene and variants in this gene are modifying factors for melanoma risk in CDKN2A mutation carriers." (PMID 24742402, 2014). "We also studied the presence of CDKN2A mutation in patients belonging to the familial melanoma group and compared clinical and histopathological characteristics of 17 patients with CDKN2A mutation and 168 non-carriers." (PMID 25893138, 2014). "Melanoma cases with thinner tumours appeared to have an increased prevalence of CDKN2A mutations in the UK sample set in which there was a greater proportion of thicker tumours than in the other two studies (in part because of an ascertainment choice)." (PMID 25780468, 2014). "Recurrent CDKN2A mutations have been identified in melanoma families, mutation p.G101W being the most frequent one detected in Mediterranean pedigrees." (PMID 24742402, 2014). "The association of the CDKN2A polymorphisms with melanoma risk reported in those studies lack consistency." (PMID 23816148, 2013). "Statistically significant association with melanoma risk was also observed for the carriers of the variant T-allele of rs3088440 (540 C>T) at the 3’ UTR of CDKN2A gene with an OR 1.52 (95% CI 1.14-2.04)." (PMID 23816148, 2013). "Identified high-penetrance variants for melanoma risk include cyclin-dependent kinase inhibitor 2A (CDKN2A), cyclin-dependent kinase 4 (CDK4), an alternate reading frame (ARF) of CDKN2A, and a locus on 1p22." (PMID 24392023, 2013). "When looking at melanoma families, CDKN2A/p16 germline mutations are found in roughly 25–40% of all melanoma worldwide." (PMID 23796690, 2013). "The influence of variants at the 9p21 locus on melanoma risk has been reported through investigation of CDKN2A variants through candidate gene approach as well as by genome wide association studies (GWAS)." (PMID 23816148, 2013). "Out of those 20%-40% of the familial melanoma is linked to chromosome 9p21 locus and a proportion of 9p21 linked families carry disease-segregating germline mutations in cyclin-dependent kinase inhibitor 2A (CDKN2A) gene." (PMID 23816148, 2013).
melanoma (continued). "Minor familial melanoma loci have been more commonly found in the general population with a lower penetrance of their germline mutation than CDKN2A and CDK4." (PMID 24416617, 2013). "The locus has also been previously investigated through candidate gene approach with particular emphasis on the CDKN2A gene for detection of variants associated with risk of melanoma." (PMID 23816148, 2013). "MTAP is located closely to the CDKN2A locus and melanoma tumours often show loss of both loci and it is therefore possible that there are interactions between these two genes." (PMID 23796690, 2013). "The association of the polymorphisms 540 C>T (rs3088440) and 500 C>G (rs11515) at the 3’ untranslated region of CDKN2A with melanoma risk investigated by candidate gene approach has remained ambiguous." (PMID 23816148, 2013). "In 1994, the cyclin-dependent kinase N2A (CDKN2A) gene was identified, and it is now hold as a high-risk melanoma locus." (PMID 23634303, 2013). "Of the other 15 variants selected through tagging SNP approach to fine map CDKN2A gene we found an association between the rs3088440 variant and melanoma risk." (PMID 23816148, 2013). "In familial melanoma, which represents 8 to 12% of all melanomas, germline mutations in the CDKN2A gene are found in 20–40% of cases." (PMID 24416617, 2013). "A region between MTAP and CDKN2A is associated with both the number of cutaneous nevi and melanoma risk." (PMID 24392023, 2013). "The role of CDKN2A on melanogenesis is mainly explained by the presence of germline mutations in a proportion of familial melanoma." (PMID 23816148, 2013). "Another interesting finding is the loss of 9p21 (including tumor suppressor genes CDKN2A, CDKN2B, and ARF) in 56% of common and 54% of dysplastic nevi that are associated with melanoma." (PMID 23125934, 2012). "The risk of melanoma in CDKN2A mutation carriers varies between populations and is higher in regions with high sun exposure and high incidence of melanoma in the general population." (PMID 22759494, 2012). "CDKN2A is the major melanoma susceptibility gene, mutated in approximately 40 % of melanoma-prone families with at least three affected members." (PMID 22978401, 2012). "Inherited mutations cause a genetic predisposition to melanoma, including mutations in cell cycle genes such as CDKN2A, CDK4, RB1 and MDM2, as well as melanocyte differentiation and activation genes such as MC1R, TYR, TYRP1 and ASIP." (PMID 22536322, 2012). "The FAMMM-pancreatic carcinoma (FAMMM-PC) association in concert with the CDKN2A germline mutation was described within these families; malignant melanoma predominated in certain of them whereas PC predominated in others." (PMID 24281205, 2010). "Five papers reported on the risk of pancreatic carcinoma in FAMMM families and discussed that families with mutations in the major melanoma gene CDKN2A should be considered for pancreatic cancer surveillance." (PMID 24281082, 2010). "It is postulated, therefore, that to become an invasive melanoma, arrest of the cell cycle caused by normal CDKN2A must subsequently be overcome by mutation or deletion of CDKN2A or by alterations to other cell cycle regulators." (PMID 20140953, 2010). "The chance of finding mutations in CDKN2A in melanoma families was examined in 385 families worldwide and found to vary widely across continents." (PMID 24281082, 2010). "The GEM study group studied lifetime risk of melanoma in CDKN2A mutation carriers present in a population-based sample and estimated the penetrance of melanoma in CDKN2A carriers as 0.28 (95% CI 0.18–0.40)." (PMID 24281082, 2010). "It thus appeared that CDKN2A mutation carriers in the general population have a lower risk of melanoma compared to carriers from multiple case families, which is probably due to the co-existence of genetic variants that affect risk." (PMID 24281082, 2010).
melanoma (continued). "This gene, named CDKN2X, localized to the region of LG V expected to contain the Diff locus, and was also an attractive candidate for Diff because of the well established association of CDKN2A mutations with susceptibility to melanoma in humans." (PMID 20230482, 2010). "Of particular interest however is that a “hit” on chromosome 9, near to CDKN2A, is associated both with melanoma risk and nevus number." (PMID 24281082, 2010). "CDKN2A/p16INK4a is frequently altered in human cancers and it is the most important melanoma susceptibility gene identified to date." (PMID 19149898, 2009). "CDKN2A mutations are more frequent in patients with a strong familial history of melanoma (three or more affected family members; 35.5%) compared with patients without any history (8.2%)." (PMID 19828018, 2009). "Inherited mutations of the CDKN2A tumour suppressor gene have been reported in pancreatic cancer patients with a family history of melanoma." (PMID 19826425, 2009). "It is well established that familial melanoma patients display mutations in the tumor suppressor protein p16 (CDKN2A) in almost half of the cases." (PMID 19642975, 2009). "MC1R variants have been associated with melanoma risk among individuals of European descent and as a modifier of melanoma risk in CDKN2A mutation-positive CMM families." (PMID 18803848, 2008). "This is illustrated by the observation that in melanoma families a substantial proportion carry mutations in the CDKN2A tumour suppressor gene." (PMID 18813259, 2008). "Two high penetrance melanoma susceptibility genes, CDKN2A and CDK4, and a low penetrance gene, MC1R, have been identified." (PMID 18803811, 2008). "Germline mutations of the CDKN2A gene are found in < 25% of melanoma-prone families and there are only seven families with mutation of the CDK4 gene reported to date." (PMID 18803811, 2008). "Although approximately 50% of melanoma-prone families display linkage to 9p21, only about half of these have been identified as carriers of a mutation in the CDKN2A gene." (PMID 18612309, 2008). "The finding of the 5′UTR variant within KLHL9, located 630 kb from CDKN2A on 9p21 in one melanoma patient was serendipitous." (PMID 18612309, 2008). "Germline CDKN2A mutations have been detected in 10–25% of melanoma-prone families from North America, Europe and Australia." (PMID 18803811, 2008). "It is known that germline mutations in CDKN2A are the most common cause of inherited susceptibility to melanoma." (PMID 22275959, 2008). "About 20% of melanoma-prone families bear a point mutation in the CDKN2A locus at 9p21, which encodes two unrelated proteins, p16INK4a and p14ARF." (PMID 18612309, 2008). "In conclusion, although approximately 50% of melanoma-prone families display linkage to 9p21, only about half of these have been identified as carriers of mutations in the CDKN2A gene by direct exon sequencing." (PMID 18612309, 2008). "The low incidence of CDKN2A mutations found in primary melanomas is concordant with previous reports." (PMID 15819981, 2005). "In contrast, CDKN2A is deleted or mutated in human sporadic melanomas and derived cell lines, and it appears to be the predisposing mutation in some familial melanoma kindreds." (PMID 15819981, 2005). "In contrast, melanomas cell lines show a high incidence of mutations in CDKN2A, with homozygous deletion being the main mechanism of alteration." (PMID 15819981, 2005). "Rare mutations in the CDKN2A gene at chromosome 9p21 underlie disease susceptibility in up to 40% of multiply affected melanoma families." (PMID 12799637, 2003). "We analysed 15 Italian melanoma families for germ line mutations in the coding region of the CDKN2A gene and exon 2 of the CDK4 gene." (PMID 11556834, 2001). "One of the most common melanoma-related CDKN2A mutations reported in North America is the V126D mutation." (PMID 11506491, 2001).
melanoma (continued). "The overall incidence of CDKN2A mutations was 33.3%, but this percentage was higher in families with 3 or more melanoma cases (50%) than in those with only 2 affected relatives (25%)." (PMID 11556834, 2001). "CDK4/6 inhibitors may be a future treatment modality for glioma patients with pathogenic CDKN2A variants causing melanoma-astrocytoma syndrome detected here in one CDKN2A GV carrier with an anaplastic astrocytoma and a melanoma." (PMID 41546701, 2026). "Notably, another study uncovered the molecular mechanism linking the loss of the CDKN2A tumor suppressor to melanoma invasion and metastasis." (PMID 41596618, 2026). "The importance of CDKN2A/B chromosomal loss has since already been established as precision medicine target in other malignancies, such as melanomas, 10 non-small lung cancer, 38, 39 and urothelial carcinoma 41 by reconstituting the tumor suppressing effect of CDKN2A/B." (PMID 41438586, 2026). "Around 25% of cases with a family history of melanoma carry germline pathogenic variants (PV) in the CDKN2A gene, encoding p16INK4a and p14ARF and for a similar fraction of cases, linkage to the CDKN2A locus is observed without detection of the underlying PV/genetic alteration." (PMID 40072281, 2025). "Interestingly, genetic alterations in CDKN2A gene are frequently found in both familial and sporadic pancreatic cancer while in melanoma, this gene is mostly associated with the familial form." (PMID 39609109, 2025). "Indeed, while the overall probability to find a germline CDKN2A mutation in people with melanoma is lower than 2%, this value raises up to 20–40% in familial melanomas." (PMID 40869905, 2025). "One study identified acquired oncogenic mutations in NRAS and the loss of CDKN2A in BRAF-V600E-mutant melanoma tumors from two patients who progressed on BRAF/MEK inhibitors, suggesting that the reactivation of MAPK and the activation of cell cycle pathways contribute to resistance." (PMID 40282469, 2025). "Additionally, 19 tumours (35.2%) exhibited loss of 9p21 (CDKN2A), including three with homozygous deletion, and all but one were classified as melanoma." (PMID 40107205, 2025). "However, the fraction of melanoma cases with underlying inherited predisposition by alterations in these genes is relatively low compared to CDKN2A, and in about 50% of familial cases of malignant melanoma, the underlying cause remains unexplained." (PMID 40072281, 2025). "We detected clonal mutations of all types that affected genes known to contribute to melanoma initiation, including hotspot SNVs in Kras and Gnaq, SNVs in frequently mutated sites of Sf3b1 and Tfap2a, homozygous deletion of Cdkn2a, and amplifications of Met, Braf, Mitf, Kras, Cdk4, and Erbb3." (PMID 40950124, 2025). "Genetic studies have identified common mutations in melanoma, including cyclin-dependent kinase inhibitor 2A (CDKN2A), neuroblastoma rat sarcoma viral oncogene homolog (NRAS), phosphatase and tensin homolog (PTEN), and BRAF, with the latter being the most frequent oncogenic mutation." (PMID 40868149, 2025). "Germline mutations in CDKN2A increase the risk of melanoma by 65‐fold." (PMID 39609109, 2025). "In addition of the accurate described CDKN2A gene, there are other genes found in literature that are associated with both melanoma and pancreatic cancers." (PMID 39609109, 2025). "Familial melanoma with CDKN2A mutation (or loss of heterozygosity) has long been known." (PMID 40361349, 2025). "More rarely, other genes such as CDKN2A, associated with melanoma and pancreatic carcinoma syndrome, may be identified by MGPT." (PMID 40361347, 2025). "Loss of CDKN2A (encoding p16^INK4A) has been shown to cooperate with NRAS mutations to induce melanoma and may play a role in malignant progression." (PMID 41294657, 2025). "Similarly, CDKN2A mutations or deletions are associated with adverse outcomes in BRAF-mutant melanoma." (PMID 40332392, 2025).